APP (amyloid beta precursor protein)
Diseases named in the same sentence as APP in open-access papers (continued):
Sharing a sentence is not in itself a finding about the gene and the disease.
amyloid (continued). "We suggest that the beneficial effect of sylimarin in the AD model is related to its capacity to disaggregate amyloid plaques and to suppress APP expression." (PMID 24460990, 2014). "Further, we demonstrated that there is a positive correlation among soluble APP metabolites, which diminishes with amyloidosis." (PMID 24646516, 2014). "Amyloid plaques were distributed throughout the whole cortex of 5 months old APP/PS1 transgenic mice, some of them were small, dense core plaques and some were larger plaques with a dense core and a large halo of diffuse amyloid." (PMID 24034629, 2013). "Other studies have indicated that CCL2 expression accelerates amyloidosis in an amyloid precursor protein (APP)/CCL2 bigenic mouse model, suggesting a different role of CCL2 in resident microglia and ultimately the AD pathology of these mice." (PMID 23866683, 2013). "Mutations in presenilin 2 are rare but are also thought to affect the processing of APP toward amyloidosis." (PMID 23801962, 2013). "The amyloid plaques comprise aggregated amyloid-beta (Aβ) peptides that are generated by sequential cleavage of amyloid precursor protein (APP) by β-secretase/BACE1 and the presenilin (PSEN)-containing γ-secretase complex." (PMID 24009553, 2013). "For example, on the one hand, environmental enrichment attenuates Aβ plaques in TgCRND8 mice, on the other hand, environmental enrichment exacerbates amyloid plaque formation in APP/PS1 transgenic mice." (PMID 23326437, 2013). "APP/PS1 double transgenic mice develop early-onset amyloidosis, as young as 3 months, with plaque deposits by 5–6 months, progressing with age up to 15 months." (PMID 23536825, 2013). "Compound [11C]56b showed in vivo specificity for Aβ in the brains of PS1/APP transgenic mice, and it was subsequently shown to bind specifically to amyloid deposits in human AD brain homogenates." (PMID 23766818, 2013). "The APP/PS1 transgenic mice had advanced amyloid pathology across the brain, as well as inflammation and synaptic deficits surrounding the amyloid plaques." (PMID 24358348, 2013). "Accumulation of amyloid plaques composed of amyloid β peptide (Aβ), derived from amyloid precursor protein (APP) by consecutive actions of β- and γ-secretases is a major hallmark of AD." (PMID 23531149, 2013). "Deletion of Beclin 1 in mice has been reported to increase Aβ deposits, to decrease neuronal autophagy and to promote neuronal degeneration, while gene therapy using lentivirus expressing Beclin 1 reduces amyloid pathology in APP transgenic mice." (PMID 23951225, 2013). "We studied APP/PS1 mice at an age when amyloid pathology is extensively present throughout the entire brain and we used a whole brain seed correlation analysis to demonstrate a significant decrement in overall brain FC compared to WT mice." (PMID 24358348, 2013). "Previous reports have studied the effect of minocycline on the full-blown amyloid pathology in APP Tg mice." (PMID 22472085, 2012). "Our DC cell therapy was capable of producing a significant antibody titer, initiating amyloid plaque clearance, and providing cognitive benefit to APP+PS1 mice." (PMID 23226497, 2012). "Transgenic mice, over-expressing the mutated human amyloid precursor protein (APP) gene, provide a valuable tool for investigating the associations between amyloidosis, neuronal dysfunction, and cognitive impairment." (PMID 22697412, 2012). "In AD, extracellular deposition of the ∼4 kDa amyloid-β (Aβ) peptide derived from the amyloid precursor protein (APP), leads to amyloid plaques and neurotoxic oligomers that impair long term potentiation (LTP) and synaptic function." (PMID 22457776, 2012). "The reduced extracellular Aβ from KLC1-reduced hESC derived human neural cultures agrees with reports of reduced amyloid plaque loads following mechanical disruptions in axonal transport in the perforant pathway of APP transgenic mice." (PMID 22272245, 2012).
amyloid (continued). "LPS has been shown in several studies to significantly lower amyloid load in APP/PS1 transgenic mice." (PMID 22844636, 2012). "CIA induced before the onset of amyloid pathology reduces Aβ burden over 4 months in APP/PS1 mice, presumably by enhancing the clearance and efflux of Aβ." (PMID 22029666, 2011). "A significantly higher number of bone marrow-derived microglia colocalizes with β-amyloid plaques, and the bone marrow-derived microglial cells effectively phagocytose and remove β-amyloid deposits from the brains of APP/PS1 mice." (PMID 21406112, 2011). "This strain, which over-expresses both the 695 amino acid isoform of human amyloid precursor protein (APP) with K670N and M671L mutations and presenilin 1 with the A246E mutation, has accelerated amyloidosis and plaque formation." (PMID 20630068, 2010). "Direct noninvasive in vivo imaging of plaques in APP(xPS1) transgenic mice is a very stimulating research area and the MRI-based detection of amyloid deposits is actively pursued as an alternative technique to PET imaging in preclinical research." (PMID 20953404, 2010). "Amyloid plaques are formed by the accumulation of amyloid β (Aβ), a 4 kDa peptide that is generated by sequential cleavage of amyloid precursor protein (APP) by β-secretase and γ-secretase." (PMID 20307292, 2010). "In AD transgenic models in which ADAM10 is over-expressed, β-secretase mediated processing of APP decreases, amyloid plaque formation is lessened, and the cognitive capacities of the dual transgenic animals is improved." (PMID 20161760, 2010). "The orally active γ-secretase inhibitor LY-411575 was administered daily via gavage for 3 weeks to APP:PS1 mice with pre-existing amyloid pathology." (PMID 19419556, 2009). "Amyloid plaques are formed from amyloid β peptides (Aβ), which are cleaved by β- and γ-secretases from the amyloid precursor protein (APP)." (PMID 19936202, 2009). "Even multigenic mice that express various combinations of mutant APP and mutant tau to recapitulate the combined amyloid and tau-pathology of AD, still lack the specific regional neurodegeneration that leads to the typical brain atrophy in AD." (PMID 19794916, 2009). "To better understand the contribution of age and amyloid deposition, we have analyzed the expression of complement components during aging and their induction by amyloid deposition in brain of wildtype and plaque-forming APP transgenic mice." (PMID 19917141, 2009). "Processing of Amyloid Precursor Protein (APP) by β- and γ-secretase produces Aβ peptides and APP IntraCellular Domain, the former being the major component of AD amyloid plaques." (PMID 18764939, 2008). "Previous studies have been focused at analyzing the short-term effects (1 month) of NEP in behavioral deficits and amyloid accumulation in APP tg mice." (PMID 19014502, 2008). "A proposed mechanism for estrogen inhibition of plaque formation is that estrogen induces the cleavage of membranous amyloid precursor protein (APP) generating a soluble proteolytic fragment that precludes the development of β-amyloid plaque formation." (PMID 16122394, 2005). "The early and focal glial activation, in conjunction with upregulated BACE1 mRNA, protein and activity in the presence of its substrate APP, is proposed to represent the earliest sites of amyloid deposition, likely evolving into amyloid plaques." (PMID 16212664, 2005). "Taken together, across both bouton subtypes, the combined reduction of gains and losses was represented as an overall decrease in the dynamic fraction of axonal boutons in the APP-GFP amyloidosis group, whereas the overall number of boutons (density) remained unchanged." (PMID 40438149, 2025).
amyloid (continued). "Our study supports the hypothesis that APP and its fragments may play a key role in mitigating tau aggregation, amyloid pathology, and gliosis." (PMID 40001463, 2025). "Indeed, APP/PS1 mice show deficits in recent memory retrieval (24 hr after training) prior to amyloid plaque onset." (PMID 41269883, 2025). "The APP transgenic mouse model, which is the most widely used model and initially constructed based on the transgenic expression of the human APP gene, can develop robust amyloid pathology with memory deficits." (PMID 40507786, 2025). "APP and related amyloidosis markers may help guide clinical decision-making and improve outcomes for children with BA." (PMID 39341941, 2025). "Together with differences in intestinal microbial status, distinct levels of Aβ accumulation and the extent of inflammation probably also underlie the apparently irreconcilable motility phenotypes reported in 5xFAD mice and other APP/PS1 models with amyloid pathology." (PMID 40051115, 2025). "On the one hand, CD2AP haploinsufficiency has limited impact on Aβ accumulation in the APP/PS1 mouse model of amyloidosis, raising some doubt as to whether endocytic Aβ production from brain cells is the defining role of CD2AP in AD." (PMID 40462155, 2025). "Similarly, intracerebroventricular ABC administration to 10-month-old APP/PS1 mice markedly exacerbated the cerebral amyloid burden and maladaptive microglial activation." (PMID 40962797, 2025). "Similarly, the TgF344‐AD rat carrying mutations in APP and PSEN1 exhibits amyloid deposition, cognitive decline, and widespread neuronal apoptosis, making it a valuable model for studying late stages of AD." (PMID 40420360, 2025). "It was demonstrated that activation of Peroxisome proliferator activated receptor alpha (PPARA/PPARα) which is involved in fatty acid metabolism and in autophagy activation, decreased amyloid pathology and reversed memory deficits and anxiety symptoms in APP-PSEN1ΔE9 mice." (PMID 41123674, 2025). "Therefore, of all the genes included in our fibrosis panel, APP and genes related to APP regulation and amyloidosis appeared to be the most interesting." (PMID 39341941, 2025). "Interestingly, pioglitazone-loaded nanocarriers show greater efficacy than freely delivered pioglitazone against amyloid pathology in APP/PS1 mice." (PMID 41146261, 2025). "Moreover, adoptive transfer of Aβ-reactive effector T cells accelerates cognitive impairment and amyloid pathology in APP/PS1 mice." (PMID 41009574, 2025). "To directly measure the impact on amyloid-related processes, we cross-bred the Ms4a6d knock-out mice with AD-like transgenic line APP/PS1, and performed intracerebral microdialysis to assess Aβ clearance efficiency in 1-month-old mice before the formation of amyloid deposits." (PMID 40877951, 2025). "These transgenic mice overexpress a mutated form of the human amyloid precursor protein (APP) gene with the Swedish mutation (APPswe KM670/671NL), leading to the overproduction of β-amyloid (Aβ) peptides and their accumulation in amyloid plaques, a typical pathological hallmark of AD." (PMID 40313591, 2025). "APP/PS1 mice begin to develop cerebral amyloid pathology as early as 6–8 weeks of age." (PMID 39861162, 2025). "This time frame matches with the early symptomatic pre-plaque stages of APP-related amyloidosis." (PMID 40313591, 2025). "Therefore, early upregulation of A2AR in a hippocampal environment of ongoing amyloid pathology worsens the behavioural phenotype of APP/PS1 mice." (PMID 38964748, 2024). "Additionally, research on APP/PS1 mice indicates that therapeutic PE can reduce amyloid plaque load and preserve vascular health, suggesting a beneficial effect on AD pathology." (PMID 39421573, 2024). "Mice do not spontaneously develop amyloid pathology: hence, transgenic mice express human genes associated with familial AD mutations, namely in APP and PS1, under the assumption that the same pathways are involved in sporadic AD." (PMID 38892408, 2024).
amyloid (continued). "Therefore, the induction of APP indicates the potency of LPS to induce amyloidosis in our experimental system." (PMID 39796150, 2024). "In the present study, we observed no transgene-related difference in the levels of most F2-IsoPs, contrasting with a previous report of higher 8,12-iso-iPF2α-VI (5(RS)-5-F2c-IsoP) levels in the cortex and hippocampus of Tg2576 APP mice correlating with amyloid deposits." (PMID 39490923, 2024). "Likewise, the Amyloid precursor protein (APP), associated to amyloid plaque formation and Alzheimer, has been found to promote angiogenesis, stimulating ECs migration, proliferation and formation of new vessels, at least in vitro." (PMID 39004727, 2024). "However, this was not demonstrated directly, relying instead on citation of prior work involving a triple knock-in mouse model of aggressive amyloidosis, APP NL-G-F." (PMID 39315091, 2024). "Compared to APP mutations only mouse models, this mouse model produced robust and accelerated amyloid pathology with no tau pathology." (PMID 38462606, 2024). "Moreover, the amyloid deposition patterns in the brain of 16-week-old 3xTg AD or APP/PS/Tau AD mice were considerably different from those of 36-week-old 3xTg AD or APP/PS/Tau AD mice." (PMID 38895620, 2024). "The amyloid pathology of APP/PS1‐Tg rats was confirmed through two independent strategies." (PMID 38379185, 2024). "However, during the onset of amyloid pathology, only female APP/PS1 mice had vascular stiffness in the aorta." (PMID 38862757, 2024). "We first determined whether elevated hippocampal activity could be detected in juvenile (6 week-old) mice in a well-studied animal model of AD-related amyloidosis, the APP/PS1 strain." (PMID 39262788, 2024). "The effect of amyloid pathology on increasing tau‐induced neuronal damage has been reported in transgenic mice overexpressing mutant tau in the entorhinal cortex and crossed with APP/PS1 mice." (PMID 38148705, 2024). "However, during the onset of amyloid pathology (7-month-old), both female and male APP/PS1 mice showed a restoration or a “functional catch-up mechanism” of the ACh-induced relaxation compared to the 3-month-old mice." (PMID 38862757, 2024). "Choline supplementation has been shown to improve behavioral deficits in the APP.PS1 AD mouse model at 11 months of age but the effects of choline supplementation on amyloidosis and behavior in the AppNL-G-F mouse model, and any AD mouse model, have not been studied across life." (PMID 38315685, 2024). "Similarly, the selective expression of human APOE4 in microglia in the APP/PS1 amyloidosis model leads to increased lipid accumulation in APOE4 microglia compared to those expressing APOE3." (PMID 39595034, 2024). "In order to examine potential sex-related differences in learning and memory as a function of age and the presence of amyloidosis, we assessed the recall deficits, if any, on cFC in male and female APP/PS1 mice at different ages (2, 4, 6, 8, 10, and 12 months)." (PMID 37045867, 2023). "Notably, 6KApoEp-treated APP/PS1/E4 mice demonstrated significant amelioration of cerebral amyloid pathology versus 6KApoEp-treated APP/PS1/E2 or APP/PS1/E3 mice." (PMID 37211092, 2023). "APP is cleaved by α- and γ- secretase to prevent Aβ formation in the non-amyloidosis pathway." (PMID 36774494, 2023). "One possibility is that amyloid plaque clearance may be relatively more effective in 5xFAD mice than in APP KI mice." (PMID 37536983, 2023). "In the current study, we used the same mature-onset Tet-Off APP mouse model as in our previous work on functional neuronal networks, to investigate potential changes in glymphatic dynamics at advanced stages of amyloidosis." (PMID 36707887, 2023). "The lack of efficacy of anakinra in the APPNL-G-F could be related to the aggressiveness of this model, that it has been shown to develop a more accelerated AD, with a more important amyloid pathology than the APP/PS1 model." (PMID 37187754, 2023).
amyloid (continued). "Indeed, recent evidence has shown that myelin damage induced in mouse models of amyloidosis are also capable of driving Aβ deposition by shifting neuronal APP metabolism and by altering the microglial phenotype." (PMID 37024484, 2023). "Moreover, pharmacological treatment with 33i, improved cognitive dysfunction and long-term potentiation, reducing amyloid pathology and neuroinflammation in the APP/PS1 AD mouse model." (PMID 37698780, 2023). "Here, we show that cGP improves spatial memory and reduces amyloid plaque burden in APP/PS1 mice." (PMID 36909366, 2023). "Therefore, astrocyte-dependent rescue of slow waves reduced the rate of amyloid plaque deposition in APP mice." (PMID 37567942, 2023). "MiR-346, miR-101, miR-101a-3p, and miR-384 are known to inhibit APP production (and consequently, amyloid plaque generation) via their actions on either the 3′ or 5′ UTRs of the APP gene, and these microRNAs have been noted to be downregulated in animal models and AD subjects." (PMID 37569871, 2023). "Thus, we assessed the effects of cGP on amyloid pathology in the hippocampus and cortex of APP/PS1 mice." (PMID 36909366, 2023). "The amyloidosis process of APP in the central nervous system may lead to the degeneration of motor neurons." (PMID 36707813, 2023). "Next, we analyzed whether CTB treatment affected the amyloid load in the hippocampi of APP/PS1 mice." (PMID 37759382, 2023). "Additionally, in vivo evidence from amyloid mice model APP/PS1 showed SOD inactivation, which aggravated mitochondrial dysfunction, enhanced oxidative stress and promoted apoptosis." (PMID 37507998, 2023). "APP/PS1 mice are widely used in AD research because they model well the pathological changes of AD such as senile plaque, neuronal deletion, amyloid-associated inflammation and cognitive decline." (PMID 35992591, 2022). "Moreover, GFP+ cells in the brain parenchyma do not express Tmem119, a microglia-enriched transcript that is detectable in APP/PS1 brains but downregulated in the 5XFAD model of accelerated amyloid pathogenesis." (PMID 35511433, 2022). "It has been reported that it closely correlates with amyloid pathology, infiltrates Aβ-containing plaques and contributes to amyloidosis while iron+ cells cluster around Aβ plaques in tissue from AD patients, as they do in tissue from APP/PS1 mice." (PMID 35875349, 2022). "Meanwhile, high concentrations of Aβ may induce APP synthesis and trigger amyloidosis in peripheral neurons." (PMID 35209007, 2022). "PSs are the crucial catalytic components of γ-secretase, and mutations in PS1 are causative in the majority of familial AD (FAD) cases, likely through a yet-unclear loss of function, while APP overexpression or mutations are causative of FAD, likely favoring amyloidosis and tauopathy." (PMID 36012187, 2022). "To produce an AD mouse model that genetically lacks microglia, we crossed FIRE knockout mice with 5xfAD transgenic mice that harbor familial AD mutations in amyloid precursor protein (APP) and presenilin 1 (PSEN1) and develop robust parenchymal amyloid pathology." (PMID 35705056, 2022). "Whereas we cannot point towards a specific reason, it is feasible that using two mice colonies might account for the differences observed in amyloid plaque size and therefore control APP/PS1 mice are used for both colonies." (PMID 36345028, 2022). "As a consequence, BACE1 could lose its capacity to cleave APP, consequently reducing Aβ peptide production and amyloid plaque accumulation." (PMID 35773306, 2022). "Broad-spectrum antibiotics cocktails applied in two mouse models of AD-like amyloidosis (APP/PS1 and APPPS1) yielded a profound alteration of the microbiota composition, notably of Lachnospiraceae and S24-7 genera, and a significant decrease in cerebral amyloidosis." (PMID 35248147, 2022).